TNFRSF8 (TNF receptor superfamily member 8)
Description:
Receptor for TNFSF8/CD30L. May play a role in the regulation of cellular growth and transformation of activated lymphoblasts. Regulates gene expression through activation of NF-kappa-B.
Synonyms: CD30; D1S166E; KI-1
Tractability: Antibody: a drug acting on it is in phase 2 or 3 trials; UniProt places it where antibodies can reach, with high confidence; its Gene Ontology location is reachable by antibodies, with high confidence; UniProt predicts a signal peptide or a membrane-spanning region; the Human Protein Atlas places it where antibodies can reach. PROTAC: ubiquitination databases record sites on it; its protein half-life has been measured. Other modalities: an approved drug acts on it.
Target class: Secreted protein
Gene: Protein-coding gene on chromosome 1 (12,063,303 to 12,144,207, forward strand). Ensembl gene ENSG00000120949.
Subcellular location: Cell membrane (Isoform 1); Cytoplasm (Isoform 2)
Subcellular location (Human Protein Atlas): Plasma membrane
Pathways (Reactome):
Immune System: TNFs bind their physiological receptors
Gene Ontology:
Molecular function: protease binding; protein binding; transmembrane signaling receptor activity
Biological process: cellular response to mechanical stimulus; positive regulation of apoptotic process; positive regulation of TRAIL production; positive regulation of tumor necrosis factor production; negative regulation of cell population proliferation; signal transduction
Cellular component: cytoplasm; extracellular exosome; plasma membrane
Genetic constraint (gnomAD): Loss-of-function variants: 27 observed, 69.52 expected, observed/expected ratio (o/e) 0.39, 90% interval 0.28 to 0.54. The upper end of that interval is the gene's LOEUF score, 0.54, which puts it in group 2 of 6, group 1 being the genes least tolerant of losing a copy. Missense variants: 720 observed, 803.13 expected, observed/expected ratio (o/e) 0.9, 90% interval 0.84 to 0.95. Synonymous variants: 356 observed, 335.08 expected, observed/expected ratio (o/e) 1.06, 90% interval 0.97 to 1.16.
Homologues: Orthologues: chimpanzee TNFRSF8 (96% identical), macaque TNFRSF8 (93% identical), rabbit TNFRSF8 (64% identical), dog TNFRSF8 (63% identical), mouse Tnfrsf8 (49% identical), rat Tnfrsf8 (47% identical), zebrafish tnfrsf1b (11% identical), zebrafish tnfrsf11a (10% identical), zebrafish hdr (10% identical), zebrafish cd40 (9% identical), zebrafish tnfrsfa (8% identical). Paralogues in human: TNFRSF1B (17% identical), TNFRSF21 (14% identical), LTBR (13% identical), TNFRSF1A (12% identical), TNFRSF11A (11% identical), NGFR (11% identical), TNFRSF4 (11% identical), TNFRSF6B (10% identical), CD40 (10% identical), TNFRSF11B (10% identical), TNFRSF25 (9% identical), RELT (9% identical), and 9 more.
Diseases named in the same sentence as TNFRSF8 in open-access papers:
TNFRSF8 is named in the same sentence as 307 diseases in open-access papers, as found by Europe PMC text mining. Sharing a sentence is not in itself a finding about the gene and the disease. The quoted sentences say what the papers report.
lymphoma (368 papers, 1991 to 2026). A malignant (clonal) proliferation of B- lymphocytes or T- lymphocytes which involves the lymph nodes, bone marrow and/or extranodal sites. "al. also noted the increased expression of STAT3, GZMB and TNFRSF8 (CD30) as important markers of the HIV+ lymphomas." (PMID 40627772, 2025). "The CD30-positive lymphomas are characterized by the expression of tumour necrosis factor receptor superfamily member 8 (TNFRSF8) which is a 120-kDa type I transmembrane glycoprotein more commonly referred to as CD30." (PMID 33413671, 2021). "The region encompasses the coding sequences of MTOR, TNFRSF8 (CD30), and TNFRSF1B, which are described to have an activating role in a majority of other lymphomas, potentially suggesting a pleiotropic effect of these genes in lymphomagenesis." (PMID 38460675, 2024).
Hodgkins lymphoma (300 papers, 1991 to 2026). A heterogeneous group of malignant lymphoid neoplasms of B-cell origin characterized histologically by the presence of Hodgkin and Reed-Sternberg (HRS) cells in the vast majority of cases. "TNFSF8 (CD30L) is a ligand for the cell surface antigen and marker for Hodgkin lymphoma and related hematologic malignancies, TNFRSF8/CD30." (PMID 38773393, 2024). "TNFRSF8 (CD30) is a specific marker and target antigen for Hodgkin lymphoma." (PMID 34975912, 2021). "Brentuximab vedotin (Adcetris@), approved by FDA in 2011, composes of MMAE and cAC10 mAb (chimeric IgG1 antibody) via a protease-cleavable dipeptide linker to target tumor antigen CD30 (also known as TNFRSF8) for the treatment of Hodgkin’s lymphoma and ALCL (ki-1 lymphoma)." (PMID 31068807, 2019). "In 1982, the monoclonal antibody Ki-1 (later named TNFRSF8 or CD30) was highlighted when studying the Hodgkin and Reed–Sternberg cells of Hodgkin’s disease." (PMID 35406421, 2022). "The HABP4 was identified by cross-reactivity with Ki-1 (which recognizes CD30, =TNFRSF8), the first monoclonal antibody to identify neoplastic Hodgkin and Stenberg-Reed cells in Hodgkin’s lymphoma." (PMID 33245729, 2020).
T-cell lymphoma (124 papers, 2006 to 2026). "A study by the European T-Cell Lymphoma research group validated a three-gene model (TNFRSF8, BATF3, TMOD1) that was mostly expressed in ALK- ALCL, as revealed by RT-qPCR." (PMID 40565334, 2025). "Using RT-qPCR, a study from the European T-cell lymphoma group validated a three-gene model (TNFRSF8, BATF3, TMOD1) able to separate ALK- ALCL from PTCL, NOS." (PMID 34572893, 2021). "CD30—also known as Ki-1 or TNFRSF8—is a 120 kDa transmembrane glycoprotein receptor expressed in different types of B- and T-cell lymphomas, in plasma cells, in a subtype of activated macrophages, in myeloblasts in a subset of acute myeloid leukemia, and in some cases of myelodysplastic syndrome." (PMID 37627126, 2023). "A study from the European T-Cell Lymphoma Study Group identified a set of three genes (TNFRSF8, BATF3, and TMOD1) whose co-expression could potentially distinguish ALK-negative ALCL from PTCL-NOS, with an overall accuracy of approximately 97% in unrelated groups of patients." (PMID 38921179, 2024). "B-cell NHLs frequently express CD27/CD27L (TNFRSF7/TNFSF7), CD30 or CD30L (TNFRSF8 or TNFSF8), CD40 (TNFRSF5), and TNFRs/TNF positive (TNFRSF1 and 2/TNFSF2), but T-cell NHLs show expression of CD30, CD40L (TNFSF5), and TNFRs/TNF." (PMID 37240076, 2023).
non-Hodgkin lymphoma (48 papers, 1991 to 2025). Distinct from Hodgkin lymphoma both morphologically and biologically, non-Hodgkin lymphoma (NHL) is characterized by the absence of Reed-Sternberg cells, can occur at any age, and usually presents as a localized or generalized lymphadenopathy associated with fever and weight loss. "Serum Tnfrsf8 levels have been found to be increased in patients with autoimmune diseases and those infected with hepatitis B, hepatitis C, Epstein-Barr, and HIV, and Tnfrsf8 expression is upregulated in hematological malignancies, including Hodgkin’s and non-Hodgkin’s lymphomas." (PMID 23179634, 2013).
embryonal carcinoma (41 papers, 2005 to 2026). A non-seminomatous malignant germ cell tumor characterized by the presence of large germ cells with abundant cytoplasm resembling epithelial cells, geographic necrosis, high mitotic activity, and pseudoglandular and pseudopapillary structures formation. "TNFRSF8/CD30 was expressed in most embryonal carcinoma, whereas in only about 10% of seminoma, and was validated in our results." (PMID 36713456, 2022). "By contrast, hESCs and embryonic carcinoma cells exhibit CD30 (also known as TNFRSF8) and SOX2." (PMID 25543152, 2015). "Based on our results, we suggest that KIT, TNFRSF8, and ERBB4 may be suitable targets for the treatment of germinoma, embryonal carcinomas, and yolk sac tumors, respectively." (PMID 32999426, 2020).
B-cell lymphoma (38 papers, 2008 to 2025). "This has already been described regarding TNFRSF8, which has subtype-specific effects on the growth of T-cell and B-cell lymphoma cell lines, as well as mTOR activity, which is restricted to ABC DLBCL-s in most of the cases." (PMID 38460675, 2024).
breast cancer (15 papers, 2013 to 2025). A primary or metastatic malignant neoplasm involving the breast. "TNFRSF8 is a tumor necrosis factor with unclear contributions to breast cancer." (PMID 33216733, 2020). "Here, we found a decreased expression of TNFRSF8, similar to a recent immunohistochemistry-based study that reported a lack of CD30 expression in breast cancer." (PMID 33216733, 2020).
autoimmune disease (14 papers, 2013 to 2025). A disorder resulting from loss of function or tissue destruction of an organ or multiple organs, arising from humoral or cellular immune responses of the individual to their own tissue constituents. "CD30 (TNFRSF8) has been shown to be downregulated in other autoimmune diseases: its upregulation would further set irMyositis apart from DM43." (PMID 40759686, 2025). "Abnormal expression of TNFSF8 indicates that dysfunctional TNFSF8/TNFRSF8 signaling is involved in the pathological processes of AA, which also exists in other autoimmune diseases." (PMID 39170389, 2024). "Dysfunctional TNFSF8/TNFRSF8 signaling exists in AA and other autoimmune diseases." (PMID 39170389, 2024).
acute myeloid leukemia (13 papers, 2014 to 2024). Acute myeloid leukemia (AML) is a group of neoplasms arising from precursor cells committed to the myeloid cell-line differentiation. "High-risk FLT3-ITD mutation of acute myeloid leukemia was associated with high TNFRSF8 expression on myeloblasts." (PMID 25276823, 2014).
asthma (12 papers, 2010 to 2025). "Although research on TNFSF8 and TNFRSF8 is limited, existing studies suggest their elevation may be associated with chronic inflammatory diseases, including lupus erythematosus, asthma, rheumatoid arthritis, and atopic dermatitis." (PMID 40165483, 2025). "Several novel SNPs with large effect on asthma were identified in TNFRSF8/CD302 and BHMG1 genes." (PMID 32512817, 2020). "After this study was performed, new GWASs and functional annotation analysis have been published with new interesting asthma loci such as TNF receptor superfamily member 8 (TNFRSF8 ), and Collagen Type XVI Alpha 1 Chain (COL16A1 ), and more studies are to come." (PMID 33133517, 2020). "The credibility of results has been verified by selecting four genes (IL5RA, CCR3, IL13RA2, TNFRSF8) which were upregulated in Asthma groups, but downregulated in ART + Asthma groups, according to the log2 (fold change) value." (PMID 36998616, 2023).
Autoimmunity (9 papers, 2014 to 2024). The occurrence of an immune reaction against the organism's own cells or tissues. "TNFRSF8/CD30 has been shown to inhibit the proliferation of autoreactive effector immune cells, hence assisting the body in resisting autoimmunity." (PMID 36650470, 2023). "We observed the effect of WFA upregulating the production of TNFRSF8/CD30, a tumor necrosis factor receptor shown to limit the proliferation of autoreactive effector immune cells, therefore helping to protect the body against autoimmunity." (PMID 29479354, 2018).
leukemia (9 papers, 2015 to 2024). A malignant (clonal) hematologic disorder, involving hematopoietic stem cells and characterized by the presence of primitive or atypical myeloid or lymphoid cells in the bone marrow and the blood. "Some of these genes have been previously found to play important roles in haematopoiesis and leukaemia pathogenesis, e.g. PIM1, BCOR, TNFRSF8 and NR4A2." (PMID 26576536, 2015).
rheumatoid arthritis (7 papers, 2015 to 2025). A chronic, systemic autoimmune disorder characterized by inflammation in the synovial membranes and articular surfaces. "First, we utilized a publicly available scRNA-Seq data set and examined the expression of TNFSF8 and TNFRSF8 in immune cells residing in synovial tissues from joints of aged patients with rheumatoid arthritis (RA)." (PMID 34813503, 2022).
lung cancer (6 papers, 2017 to 2025). A malignant neoplasm involving the lung. "Tumor necrosis family receptor superfamily 8 (TNFRSF8 or CD30) is upregulated in lung cancer and is being investigated as a target for immunoPET noninvasive imaging." (PMID 37444527, 2023).
colorectal cancer (5 papers, 2017 to 2023). A primary or metastatic malignant neoplasm that affects the colon or rectum. "In general, in colorectal carcinoma progression, C4B, MBL2, CARD9, and TNFRSF8 affected DSS." (PMID 35456394, 2022).
germinoma (4 papers, 2020 to 2025). A malignant germ cell tumor arising in the central nervous system. "Based on our results, we suggest that KIT, TNFRSF8, and ERBB4 may be suitable targets for the treatment of germinoma, ECs, and YSTs, respectively." (PMID 32999426, 2020).
ovarian carcinoma (4 papers, 2017 to 2022). A malignant neoplasm originating from the surface ovarian epithelium. "After incorporating the H-/L- expression groups of ICOS, TIGIT, CD8A, and TNFRSF8, the researchers categorized the ovarian cancer samples into 4 groups." (PMID 36157232, 2022). "By integrating the expression levels of ICOS, TIGIT, TNFRSF8, and CD8A, ovarian cancer patients can be divided into 4 subgroups, which have different prognosis." (PMID 36157232, 2022). "Finally, the expression levels of ICOS, TIGIT, TNFRSF8, and CD8A were integrated for the purpose of grouping ovarian cancer samples by prognosis." (PMID 36157232, 2022).
Allergy (3 papers, 2018 to 2021). An allergy is an immune response or reaction to substances that are usually not harmful. "However, a comparison of ROC curves for all significant proteins showed that MMP-3, sCD30/TNFRSF8, sTNF-R1 are not significantly different from each other as prognostic factors of allergy." (PMID 33920429, 2021).
COVID-19 (3 papers, 2022 to 2023). A disease caused by infection with severe acute respiratory syndrome coronavirus 2. "Simultaneously, inhibitory markers were upregulated in patients with COVID-19 that potentially counterbalance the hyperactivation of the immune response, such as NT5E/CD73, PD1 and TNFRSF8/CD30." (PMID 37047248, 2023).
Sepsis (3 papers, 2015 to 2024). Sepsis is defined as life-threatening organ dysfunction caused by a dysregulated host response to infection. "In the end, we managed to formulate a signature of 7 IRGs for the prognosis of sepsis patients: − 0.465 × CCL5 + 0.215 × DEFA4 − 1.487 × NFYC + 1.055 × ESR1 − 0.737 × TNFRSF8 − 0.228 × CX3CR1 + 1.003 × SERPINA3." (PMID 36650470, 2023). "Low expression of ARHGEF10L in CD14 + monocytes is associated with increased death from sepsis, and the list included genes related to anti-bacterial activity (LCN2), regulation of TLR4 responses (SLC15A3), LPS sensitivity and autophagy (RUBCNL and SLC8A1) and apoptosis (FAS, TNFRSF21, TNFRSF8)." (PMID 39730996, 2024). "Although little is known about the roles of NFYC, TNFRSF8 and SERPINA3 in sepsis, NFYC is characterized as a new regulator of skeletal muscle immunometabolic signaling." (PMID 36650470, 2023).
co-infection (2 papers, 2015 to 2019). "qRT-PCR also demonstrated co-infection significantly increased expressions of CASP2, CASP3, BC2L11, FASLG, and TNFRSF8." (PMID 25906258, 2015).
Insulin resistance (2 papers, 2022 to 2025). Increased resistance towards insulin, that is, diminished effectiveness of insulin in reducing blood glucose levels. "These genes have been involved in insulin resistance and secretion (ATM, PTPRN2, PSMD10, and NSF), adipogenesis (SLC25A24 and PAX8), inflammatory processes (TNFRSF8 and SLIT3), and mitochondrial processes (PM20D1 and LCLAT1)." (PMID 36535927, 2022).
periodontitis (2 papers, 2019 to 2023). An acute or chronic inflammatory process that affects the tissues that surround and support the teeth. "In serum, RA subjects with moderate/severe periodontitis had significantly higher levels of APRIL (TNFSF13) (p = 0.013), sCD30 (TNFRSF8) (p = 0.048) and gp130 (sIL-6Rß) (p = 0.01) compared to patients with no/mild form of periodontitis." (PMID 31072030, 2019). "Levels of sCD30/TNFRSF8, IFN-α2, IL-19, IL-26, MMP-1, gp130/sIL-6Rß, and sTNF-R1 were significantly higher in serum or GCF, and April/TNFSF13 was significantly higher in serum and saliva samples in moderate/severe periodontitis." (PMID 31072030, 2019). "In the present study, the levels of sCD30 (TNFRSF8), sTNF-R1, gp130 (sIL-6Rß), IL-19, IL-26 and MMP-1 were increased in serum, saliva or GCF samples from subjects with moderate/severe periodontitis as compared to no/mild disease." (PMID 31072030, 2019).
Cirrhosis (1 paper, 2025). A chronic disorder of the liver in which liver tissue becomes scarred and is partially replaced by regenerative nodules and fibrotic tissue resulting in loss of liver function. "Interestingly, the expression levels of CXCL13, TNFSF8, and TNFRSF8 correlated negatively with the expression of retinol binding protein 4 (RBP4), which is decreased in cirrhosis, and positively with the expression of COL1A1, which reflects liver fibrosis." (PMID 40014629, 2025).
endothelial dysfunction (1 paper, 2025). In vascular diseases, endothelial dysfunction is a systemic pathological state of the endothelium (the inner lining of blood vessels) and can be broadly defined as an imbalance between vasodilating and vasoconstricting substances produced by (or acting on) the endothelium. "The top hub genes were TNFRSF9, LZIC, TNFRSF8, SLC45A1, GPR157, and SLC25A33, induced by P. gingivalis and F. nucleatum responsible for endothelial dysfunction in brain cells." (PMID 40104076, 2025). "The top hub genes identified were TNFRSF9, LZIC, TNFRSF8, SLC45A1, GPR157, and SLC25A33, which are induced by P. gingivalis and F. nucleatum and are responsible for endothelial dysfunction in brain cells." (PMID 40104076, 2025). "Similarly, our study revealed genes like TNFRSF9, LZIC, TNFRSF8, SLC45A1, GPR157, and SLC25A33 that contribute to endothelial dysfunction in brain cells due to P. gingivalis and F. nucleatum." (PMID 40104076, 2025).
ischemia (1 paper, 2023). A hypoperfusion of the BLOOD through an organ or tissue caused by a PATHOLOGIC CONSTRICTION or obstruction of its BLOOD VESSELS, or an absence of BLOOD CIRCULATION. "Moreover, TNFRSF8 and DR6 were previously linked to renal injury and ischemia." (PMID 38137543, 2023).
kidney stone (1 paper, 2025). "Concurrently, six protein ratio pairs were found to inhibit kidney stone occurrence: GGT1/MME protein level ratio, ACE2/MME protein level ratio, ITIH3/VCAM1 protein level ratio, GZMA/TNFRSF8 protein level ratio, CRADD/HSPA1A protein level ratio and GZMA/TNFRSF4 protein level ratio." (PMID 40673688, 2025).
lung adenocarcinoma (1 paper, 2023). A carcinoma that arises from the lung and is characterized by the presence of malignant glandular epithelial cells. "IL12RB2 and TNFRSF8 are associated with the risk of lung adenocarcinoma." (PMID 37332770, 2023).
mucositis (1 paper, 2024). Mucositis is inflammation and damage of the mucous membranes lining the mouth and other parts of the gastrointestinal (GI) tract. "The potentially useful role of interleukin 12 receptor beta 2/tumor necrosis factor receptor superfamily member 8 (IL12RB2/TNFRSF8) ratio as a biomarker in the differential diagnosis between OLP and other chronic nonspecific mucositis has emerged." (PMID 38672786, 2024).
Sjögren's Syndrome (1 paper, 2024). "The interaction between TNFSF8 and TNFRSF8-triggered signaling in CD4+ T cells is involved in the pathogenesis of Sjögren's Syndrome." (PMID 39170389, 2024).